KNSTRN (kinetochore localized astrin (SPAG5) binding protein)
Diseases named in the same sentence as KNSTRN in open-access papers (continued):
Sharing a sentence is not in itself a finding about the gene and the disease.
breast carcinoma (continued). "Since KNSTRN expression is strongly positively correlated with Treg infiltration in breast cancer, targeting KNSTRN may be an effective strategy for depleting Tregs in breast cancer." (PMID 38198023, 2024). "Interestingly, multivariate Cox regression analysis revealed a significant association between KNSTRN expression and overall survival (p = 0.04425), suggesting that KNSTRN expression may be an independent prognostic factor for breast cancer." (PMID 38198023, 2024). "Therefore, we speculate that besides accelerating the cell cycle, KNSTRN may also promote breast cancer progression by enhancing the infiltration of Treg cells." (PMID 38198023, 2024). "Immunohistochemistry (IHC) was performed to evaluate KNSTRN expression in tumor and normal adjacent tissues (NAT) from TNBC patients and other breast cancer subtypes, as well as the correlation between KNSTRN expression and CD8+ T cell infiltration in TNBC." (PMID 41209020, 2025). "KNSTRN is a SPAG5-binding protein, and SPAG5 has been validated as an independent prognostic biomarker in breast cancer." (PMID 38198023, 2024). "However, the expression and biological roles of KNSTRN in breast cancers remain largely unknown." (PMID 38198023, 2024). "Immunohistochemistry was used to validate KNSTRN expression in tissue of patients with TNBC and other subtypes of breast cancer (Non-TNBC), as well as the association of KNSTRN expression and CD8+ T cell infiltration in TNBC." (PMID 41209020, 2025). "We observed higher expression of KNSTRN mRNA and protein in triple-negative breast cancer (TNBC) compared to luminal and HER2 types, indicating a potential role of elevated KNSTRN expression in driving the malignant transformation of breast cancers." (PMID 38198023, 2024). "Secondly, the in vivo effects of KNSTRN on breast cancer cell cycle and cell proliferation were not investigated." (PMID 38198023, 2024). "The overexpression of KNSTRN enhanced the expression of key cell cycle regulators, including CDK4, CDK6, and cyclin D3, thereby accelerating the G1/S phase transition and leading to aberrant proliferation of breast cancer cells." (PMID 38198023, 2024). "However, to the best of our knowledge, no studies have yet found a relationship between KNSTRN and immune infiltration in breast cancer." (PMID 38198023, 2024).
acute myeloid leukemia (2 papers, 2023 to 2024). Acute myeloid leukemia (AML) is a group of neoplasms arising from precursor cells committed to the myeloid cell-line differentiation. "In contrast, there were three tumors—acute myeloid leukemia (LAML), testicular germ cell tumors (TGCT), and thyroid carcinoma (THCA) —in which KNSTRN was downregulated in tumor tissues." (PMID 36845017, 2023).
basal cell carcinoma (2 papers, 2019 to 2021). A carcinoma involving the basal cells. "Moreover, KNSTRN [Kinetochore Localized Astrin (SPAG5) Binding Protein], which was essential for the mitotic spindle, faithful chromosome segregation and progression into anaphase, was reported to be involved in pathogenesis of leukemias, basal cell carcinoma." (PMID 31781484, 2019).
esophageal cancer (2 papers, 2023 to 2024). A primary or metastatic malignant neoplasm involving the esophagus. "In esophageal cancer, KNSTRN expression is positively correlated with that of GSK-3β, which is associated with a poor prognosis." (PMID 36845017, 2023).
leukemia (2 papers, 2019 to 2021). A malignant (clonal) hematologic disorder, involving hematopoietic stem cells and characterized by the presence of primitive or atypical myeloid or lymphoid cells in the bone marrow and the blood. "It has been reported that KNSTRN mutations rarely occurred in other solid tumors and leukemias, which are relatively specific for skin-related cancers." (PMID 34993195, 2021).
thyroid carcinoma (2 papers, 2023 to 2024). "However, we also noted a downregulation of KNSTRN expression in thyroid carcinoma, suggesting potential variations in the functional roles of KNSTRN across different tumor types." (PMID 38198023, 2024).
colorectal cancer (1 paper, 2021). A primary or metastatic malignant neoplasm that affects the colon or rectum. "Next, we detected the expression and distribution of PARPBP, KNSTRN, and KIF2C in colorectal cancer and performed a multiplex immunofluorescence staining in TMAs." (PMID 34568334, 2021).
hepatocellular carcinoma (1 paper, 2025). A malignant tumor that arises from hepatocytes. "In lung and hepatocellular carcinomas, KNSTRN correlates with Th2 polarization and T-cell exhaustion markers." (PMID 41209020, 2025).
lung carcinoma (1 paper, 2021). "However, the expression and role of KNSTRN in lung cancer were not reported." (PMID 33976733, 2021).
pancreatic cancer (1 paper, 2025). "Immunohistochemical results showed that among the 8 CRGs: CEP55, FAM111B, MRPL3, MET, and KNSTRN had higher protein expression in pancreatic cancer tissues, while on the contrary, the protein expression of DHX30 in normal pancreas was significantly higher than that in pancreatic cancer tissues." (PMID 40677006, 2025).
prostate carcinoma (1 paper, 2024). A carcinoma that arises from epithelial cells of the prostate gland. "Similarly, the top gene set whose GSAS was different between resistant and sensitive metastatic prostate samples to abiraterone treatment was driven by KNSTRN, ECT2 and RCC2 genes, three genes previously associated with prostate cancer progression." (PMID 38597610, 2024).
rectal cancer (1 paper, 2021). A primary or metastatic malignant neoplasm that affects the rectum. "The prognostic index formula for colon and rectal cancer patients in the training cohorts was as follows: Risk score = [Status of PARPBP ∗ (-0.6921)] + [Status of KNSTRN ∗ (1.4204)] + [Status of KIF2C ∗ (-0.9696)]." (PMID 34568334, 2021).
retinoblastoma (1 paper, 2024). A malignant tumor that originates in the nuclear layer of the retina. "KNSTRN was negatively correlated with DNA repair (Cor = − 0.401, p < 0.001) in retinoblastoma and apoptosis (Cor = − 0.50, p < 0.001) in uveal melanoma." (PMID 38198023, 2024).
cancer (10 papers, 2019 to 2025). A tumor composed of atypical neoplastic, often pleomorphic cells that invade other tissues. "Elevated KNSTRN expression is linked to poor prognosis and altered immune infiltration in pan-cancers." (PMID 41209020, 2025). "KNSTRN expression was upregulated in the majority of cancers and was associated with a worse prognosis." (PMID 36845017, 2023). "Somatic mutations in KNSTRN not only cause the occurrence of malignant tumors but also promote tumor development." (PMID 36845017, 2023). "In summary, KNSTRN overexpression was associated with cancer progression and poor prognosis in LUAD." (PMID 33976733, 2021). "Studies across pan-cancer datasets indicate that high KNSTRN expression is correlated with poor prognosis and alterations in immune cell infiltration." (PMID 41209020, 2025). "Pan-cancer analysis revealed a pronounced increase in KNSTRN expression level across multiple malignancies in TCGA." (PMID 41209020, 2025). "Wound healing and Transwell assays showed that knockdown of KNSTRN in cell lines led to slowed migration, indicating that KNSTRN can promote cancer cell progression." (PMID 41209020, 2025). "The TIMER database was utilized to investigate the mRNA expression of KNSTRN in various cancer types." (PMID 38198023, 2024). "To better understand the expression of KNSTRN in tissues, we used the IHC data to assess the differential expression of KNSTRN between cancer tissues and paired normal tissues." (PMID 36845017, 2023). "We also evaluated KNSTRN expression in cancer tissues, paired normal tissues, and tissues classified according to TNM stage." (PMID 36845017, 2023). "KNSTRN affected the infiltration of multiple types of immune cells in the TIME and was closely associated with several immune-related genes in pan-cancer data." (PMID 36845017, 2023). "To fully understand the effect of KNSTRN expression on cancer prognosis, we analyzed the survival outcomes of patients with cancer in the TCGA cohort." (PMID 36845017, 2023). "The Genomics of Drug Sensitivity in Cancer database was used to evaluate the relationship between KNSTRN expression and the half maximal inhibitory concentration (IC50) of several anticancer drugs, and gene set variation analysis was performed." (PMID 36845017, 2023). "Since KNSTRN was significantly associated with immune cells and molecules in the TIME, we further evaluated the relationship between KNSTRN and the prognosis of cancer patients receiving immunotherapy." (PMID 36845017, 2023). "KNSTRN, an important component of the mitotic spindle, was found to regulate chromosome segregation and anaphase onset during mitosis in cancer cells." (PMID 34568334, 2021). "Therefore, we analyzed KNSTRN expression at the single-cell level in different cancers and explored the relationship between KNSTRN expression and tumor functional status using the Cancer SEA database." (PMID 38198023, 2024). "Among cancer tissues, KNSTRN expression was the highest in TGCT and the lowest in KIRP." (PMID 36845017, 2023). "mRNA expression, cancer patient prognosis, and correlations between KNSTRN expression and immune component infiltration were analyzed using Genotype-Tissue Expression, The Cancer Genome Atlas, Cancer Cell Line Encyclopedia, Human Protein Atlas, ImmuCellAI, TIMER2.0, and KM-Plotter." (PMID 36845017, 2023). "We first analyzed the RNA expression of KNSTRN in various cancer tissues and tumor cell lines." (PMID 36845017, 2023). "Furthermore, among cancer cell lines, the expression of KNSTRN was highest in CESC cells and lowest in CLL cells." (PMID 36845017, 2023). "In conclusion, KNSTRN may be a significant prognostic biomarker and promising target for oncotherapy in numerous cancers." (PMID 36845017, 2023). "We aimed to determine whether KNSTRN may serve as a potential pan-cancer prognostic biomarker and to explore the influence of KNSTRN on the TIME and anticancer therapy outcomes." (PMID 36845017, 2023).
cancer (continued). "Thus, the objective of the present study was to evaluate the prognostic value of KNSTRN expression in human LUAD based on data obtained from the Cancer Genome Atlas (TCGA) database." (PMID 33976733, 2021). "Interestingly, elevated KNSTRN expression affects the immune microenvironment and is a poor prognostic marker for immunotherapy response across different cancer types, inviting further investigation of the impact of KNSTRN promoter mutations on KNSTRN expression in larger tumor cohorts." (PMID 40359938, 2025). "However, other variations of KNSTRN, such as overexpression, might be involved in the development of cancer." (PMID 33976733, 2021). "It is worth noting that it was also shown that KNSTRN plays a role in UV radiation-induced apoptosis; however, the effect of the mutations on avoidance of apoptosis by BCC cells or any other cancer cells has not yet been tested." (PMID 34900699, 2021). "Additionally, KNSTRN has been mainly researched in individual tumors; pan-cancer studies on KNSTRN are lacking." (PMID 36845017, 2023).
tumor (10 papers, 2019 to 2025). "Overall, high expression of KNSTRN in most tumors led to poor prognosis, confirming that KNSTRN is a tumor risk factor." (PMID 36845017, 2023). "High expression of KNSTRN was associated with a poor prognosis in tumor patients receiving immunotherapy and was closely related to decreased sensitivity to other anticancer drugs." (PMID 36845017, 2023). "KNSTRN expression is also closely linked to the tumor immune microenvironment." (PMID 41209020, 2025). "Moreover, univariate Cox regression was also performed, and the results suggested that TNM stage, clinical stage, tumor status, primary therapy outcome, and high expression of KNSTRN were associated with poor OS (P < 0.05)." (PMID 33976733, 2021). "Additionally, KNSTRN expression is significantly negatively correlated with the immune score (P = 0.0015), indicating that higher KNSTRN expression is associated with a less immunogenic tumor microenvironment." (PMID 41209020, 2025). "Transcriptomic profiling reveals that KNSTRN-high tumors exhibit metabolic alteration within the tumor microenvironment, which potentially creating a nutrient-depleted and acidic microenvironment that can suppress T cell function." (PMID 41209020, 2025). "High expression of KNSTRN is indicative of an unfavorable outcome due to its contribution to promoting cell cycle progression and tumor cell proliferation." (PMID 41209020, 2025). "Subsequently, we examined the relationship between KNSTRN expression and immune scores, stromal scores, and tumor purity using the “ESTIMATE” package." (PMID 38198023, 2024). "In the present study, we found that KNSTRN expression was significantly positively correlated with Treg infiltration and negatively correlated with the infiltration of tumor-killing cells, such as Tgd and NK cells." (PMID 38198023, 2024). "As a molecule mainly involved in cell cycle checkpoints, DNA replication, damage repair, and other biological processes, KNSTRN has rarely been studied in relation to tumor immunity." (PMID 36845017, 2023). "We also analyzed immunofluorescence data to evaluate KNSTRN expression of distinct tumor cells at the cellular level." (PMID 36845017, 2023). "GSVA revealed that the unfolded protein response (ER stress) was significantly positively correlated with KNSTRN expression, and ER stress has been reported by several studies to be an essential contributor to anti-tumor drug resistance." (PMID 36845017, 2023). "In 27 types of tumors, KNSTRN expression in tumor tissues was upregulated compared to that in paired adjacent tissues." (PMID 36845017, 2023). "The expression analysis results showed that the expression of KNSTRN in most tumor tissues was higher than that in normal tissues." (PMID 36845017, 2023). "To address the gap in the literature regarding the role of KNSTRN in tumor immunity, we conducted a series of bioinformatics analyses." (PMID 36845017, 2023). "The SPI was calculated based the prognostic model, including BOC, GRIA3, MME, SPOCK1, and KNSTRN, which were associated with stemness, TNM stage, prognosis, and tumor microenvironment (TME)." (PMID 35360859, 2022). "Tumor status, primary therapy outcome, and KNSTRN expression were used to construct a clinical prognostic risk score for LUAD." (PMID 33976733, 2021). "Furthermore, KNSTRN expression is significantly positively correlated with tumor purity (P < 0.001), suggesting that tumors with higher KNSTRN expression tend to have a lower proportion of immune cell infiltration." (PMID 41209020, 2025). "In this dataset, we found that KNSTRN is primarily expressed in tumor cells." (PMID 41209020, 2025). "Nevertheless, the role of KNSTRN in TNBC, particularly its implications for the prognosis, immune infiltration, tumor progression, and underlying mechanisms remains unclear." (PMID 41209020, 2025).
tumor (continued). "Notably, elevated KNSTRN expression was found to be inversely correlated with immune scores and stromal scores, suggesting a reduction of immune and stromal cells within the tumor microenvironment when KNSTRN is highly expressed." (PMID 38198023, 2024). "In addition to assessing the effect of KNSTRN on tumor immunotherapy outcomes, we further analyzed the relationship between KNSTRN expression and the IC50 of 192 antitumor drugs." (PMID 36845017, 2023). "However, the role of KNSTRN in the tumor immune microenvironment (TIME) as a tumor prognostic biomarker and potential therapeutic target has not been clarified." (PMID 36845017, 2023). "However, the mechanisms by which KNSTRN promotes tumor progression and metastases in LUAD need further elucidation." (PMID 33976733, 2021). "Moreover, the relationship of KNSTRN with tumor-infiltrating immune cells in different tumor microenvironments was analyzed using single-sample gene set enrichment analysis (ssGSEA)." (PMID 33976733, 2021). "The increased expression levels of KNSTRN positively correlated with higher grades of T stage (P < 0.001), N stage (P = 0.003), M stage (P = 0.02), clinical stage (P < 0.001), tumor status (P < 0.001), and the outcome of the primary therapy (P = 0.003)." (PMID 33976733, 2021). "Recent studies also found that altered KNSTRN expression resulted in the loss of chromatid cohesion in the noncutaneous tumor cell line HeLa cells." (PMID 33976733, 2021). "The results also suggested that KNSTRN was highly expressed in tumor tissues (P < 0.001)." (PMID 33976733, 2021). "Moreover, elevated expression levels of KNSTRN are negatively correlated with immune score and tumor purity, further indicating that KNSTRN may contribute to immune suppression and a tumor-dominant microenvironment." (PMID 41209020, 2025). "Additionally, previous research has shown that KNSTRN may play a significant role in modulating the tumor immune microenvironment." (PMID 41209020, 2025). "Additionally, KNSTRN expression positively correlates with tumor purity, suggesting a possible reduction in stromal and immune cell infiltration that may limit proper CD8+ T cell activation." (PMID 41209020, 2025). "Moreover, these relationships indicated the role of KNSTRN in regulating tumor immunology in LUAD." (PMID 33976733, 2021). "KNSTRN expression in LUAD and normal tissues was analyzed, revealing a difference in the KNSTRN expression levels in LUAD and normal tissues; KNSTRN was highly expressed in tumor tissues (P < 0.001)." (PMID 33976733, 2021). "KNSTRN expression in tumor tissues was standardized using the Z-score, and the LUAD cohort was divided into high- and low-expression groups according to KNSTRN expression." (PMID 33976733, 2021). "Collectively, these results lead us to propose that KNSTRN facilitates TNBC progression potentially by driving cell cycle progression and activating the PI3K-AKT-mTOR signaling axis, thereby promoting cell proliferation and tumor growth." (PMID 41209020, 2025). "Additionally, KNSTRN expression was highly correlated with the infiltration of multiple immune components in the TIME and was related to a poor prognosis in tumor patients receiving immunotherapy." (PMID 36845017, 2023). "Furthermore, high expression of KNSTRN positively correlated with advanced clinicopathological characteristics (TNM stage, clinical stage, tumor status, and primary therapy outcome), survival time, and poor prognosis." (PMID 33976733, 2021). "The mechanisms by which KNSTRN regulates immune infiltration and tumor progression remain unclear, and its negative correlation with immune cells may involve factors like cytokine changes, metabolic alterations, and hypoxia." (PMID 41209020, 2025). "Additionally, KNSTRN expression was significantly higher in the tumor tissues of TNBC than in those of Non-TNBC patients, which is consistent with our previously results." (PMID 41209020, 2025).
tumor (continued). "By performing immunohistochemical staining on patients’ samples to further validated KNSTRN expression levels in the tumor and NAT of patients with TNBC and Non-TNBC, we observed that KNSTRN was expressed at higher levels in both TNBC and Non-TNBC tumor tissues compared to their NAT." (PMID 41209020, 2025).